Y_RNA (Y RNA )
Gene: Miscellaneous RNA gene on chromosome 9 (127,470,875 to 127,470,987, forward strand). Ensembl gene ENSG00000200788.
Homologues: Orthologues: chimpanzee Y_RNA (96% identical), macaque Y_RNA (91% identical), guinea pig Y_RNA (79% identical). Paralogues in human: RNY1 (82% identical), RNY1P11 (82% identical), Y_RNA (82% identical), Y_RNA (81% identical), Y_RNA (80% identical), Y_RNA (79% identical), RNY1P8 (78% identical), Y_RNA (78% identical), Y_RNA (77% identical), RNY1P10 (76% identical), RNY1P5 (76% identical), RNY1P7 (76% identical), and 91 more.